FIBCD1 (fibrinogen C domain containing 1)
Description:
Acetyl group-binding receptor which shows a high-affinity and calcium-dependent binding to acetylated structures such as chitin, some N-acetylated carbohydrates, and amino acids, but not to their non-acetylated counterparts. Can facilitate the endocytosis of acetylated components.
Synonyms: FLJ14810
Tractability: Small molecule: a structure with a bound ligand is known. Antibody: UniProt predicts a signal peptide or a membrane-spanning region; its Gene Ontology location is reachable by antibodies, with medium confidence.
Gene: Protein-coding gene on chromosome 9 (130,900,194 to 130,941,232, reverse strand). Ensembl gene ENSG00000130720.
Subcellular location: Membrane
Subcellular location (Human Protein Atlas): Cell Junctions
Gene Ontology:
Molecular function: chitin binding; protein binding
Cellular component: membrane; extracellular matrix
Genetic constraint (gnomAD): Loss-of-function variants: 47 observed, 39.17 expected, observed/expected ratio (o/e) 1.2, 90% interval 0.95 to 1.53. The upper end of that interval is the gene's LOEUF score, 1.53, which puts it in group 6 of 6, group 1 being the genes least tolerant of losing a copy. Missense variants: 653 observed, 638.28 expected, observed/expected ratio (o/e) 1.02, 90% interval 0.96 to 1.09. Synonymous variants: 313 observed, 278.7 expected, observed/expected ratio (o/e) 1.12, 90% interval 1.02 to 1.23.
Homologues: Orthologues: chimpanzee FIBCD1 (99% identical), macaque FIBCD1 (97% identical), pig FIBCD1 (93% identical), rabbit FIBCD1 (92% identical), rat Fibcd1 (91% identical), dog FIBCD1 (90% identical), mouse Fibcd1 (90% identical), guinea pig FIBCD1 (88% identical), tropical clawed frog fibcd1 (67% identical), zebrafish fibcd1b (66% identical), zebrafish fibcd1a (26% identical). Paralogues in human: TNR (29% identical), TNC (29% identical), TNXB (28% identical), ANGPT1 (28% identical), ANGPTL2 (28% identical), TNN (28% identical), ANGPT4 (27% identical), ANGPT2 (27% identical), MFAP4 (26% identical), ANGPTL1 (26% identical), FGL1 (25% identical), ANGPTL6 (25% identical), and 13 more.
Diseases named in the same sentence as FIBCD1 in open-access papers:
FIBCD1 is named in the same sentence as 25 diseases in open-access papers, as found by Europe PMC text mining. Sharing a sentence is not in itself a finding about the gene and the disease. The quoted sentences say what the papers report.
gastric cancer (2 papers, 2022 to 2025). A primary or metastatic malignant neoplasm involving the stomach. "FIBCD1 has been found to be upregulated in gastric cancer and hepatocellular carcinoma and is associated with poor prognosis in patients with these cancers." (PMID 40695783, 2025). "Several reports revealed FIBCD1 association with cancer, with its overexpression linked to poor prognosis in gastric cancer and hepatocellular carcinoma." (PMID 35916241, 2022).
allergic rhinitis (1 paper, 2022). Inflammation of the nasal mucous membranes caused by an IgE-mediated response to external allergens. "Intriguingly, signs of immune system symptoms such as recurring allergic rhinitis, sinusitis and pneumonia in both patients are in line with the literature describing FIBCD1 in immune responses." (PMID 35916241, 2022).
cognitive decline (1 paper, 2020). "The gene FIBCD1 encodes for Fibrinogen C Domain-Containing protein 1 which was previously reported as associated with CNS inflammation, cognitive decline and inhibition of repair." (PMID 33282526, 2020).
colitis (1 paper, 2023). Inflammation of the colon. "Based on FIBCD1’s ability to dampen inflammatory responses in mucosal tissues, we hypothesized that enhanced FIBCD1 expression would lead to decreased intestinal inflammation and reduce the development of colitis-associated colon cancer." (PMID 38090485, 2023).
colon adenocarcinoma (1 paper, 2023). "By accessing public data repositories, we further evaluated FIBCD1 expression in colon adenocarcinoma and explored survival outcomes associated with FIBCD1 expression." (PMID 38090485, 2023).
colon cancer (1 paper, 2023). "Our analysis of publicly available resources indicates that FIBCD1 expression is increased in colon cancer compared to normal tissues, and elevated FIBCD1 expression is linked to a poorer survival prognosis." (PMID 38090485, 2023).
colonic tumors (1 paper, 2023). "To determine whether FIBCD1 is expressed in human colorectal cancer tissue and to evaluate the extent of FIBCD1 expression in relation to disease progression, we performed immunohistochemical staining of colonic tumor specimens isolated from patients diagnosed with CRC stage I-III." (PMID 38090485, 2023).
colorectal cancer (1 paper, 2023). A primary or metastatic malignant neoplasm that affects the colon or rectum. "In agreement with this, our immunohistochemical analysis of colorectal cancer tissue showed increased expression of FIBCD1 at later tumor stages." (PMID 38090485, 2023).
complex neurodevelopmental disorder (1 paper, 2022). A disorder that involves more than one phenotype associated with the central nervous system, including but not limited to intellectual disability, autism, and seizures (epilepsy). "Whole‐exome sequencing of two patients with idiopathic complex neurodevelopmental disorder (NDD) identified biallelic variants of unknown significance within FIBCD1, encoding an endocytic acetyl group‐binding transmembrane receptor with no known function in the central nervous system." (PMID 35916241, 2022).
fungal infection (1 paper, 2022). "Using a transgenic mouse overexpressing FIBCD1 in intestinal tissues, FIBCD1 was shown to regulate the gut mycobiome content and lung immune responses to fungal infection presumably through its chitin‐binding properties." (PMID 35916241, 2022).
Hyperglycemia (1 paper, 2025). An increased concentration of glucose in the blood. "Further transcriptomic and qPCR analyses identified that FIBCD1 was highly expressed in BC-DM tumor tissues and in BC cells under hyperglycemia conditions." (PMID 40695783, 2025). "Collectively, these results suggest that hyperglycemia-induced FIBCD1 activates production of PDH, which catalyzes the generation of acetyl-CoA, thus increasing H3K27ac level and promoting MCM5 expression." (PMID 40695783, 2025). "In this study, we found that hyperglycemia upregulated the expression of FIBCD1, which activated MCM5 expression to affect cell cycle and proliferation via the PDH-acetyl-CoA axis." (PMID 40695783, 2025). "In contrast, when FIBCD1 was silenced, the effects of hyperglycemia on cell proliferation, invasion, and migration of BC cells were partially reversed." (PMID 40695783, 2025). "To investigate the biological functions of hyperglycemia-induced FIBCD1, we cultured BC cells under euglycemic and hyperglycemia conditions, respectively." (PMID 40695783, 2025). "Mechanistically, hyperglycemia-activated FIBCD1 promoted MCM5 expression to induce S-phase cell cycle arrest by upregulating histone H3K27ac levels in MCM5 promoter via the PDH-acetyl-CoA axis." (PMID 40695783, 2025). "Here, we showed that FIBCD1 was upregulated in BC-DM and under hyperglycemia conditions." (PMID 40695783, 2025). "Importantly, the rescue effects of si-MCM5 on FIBCD1-mediated cell cycle dysregulation were stronger under hyperglycemia conditions than that of physiological culture conditions." (PMID 40695783, 2025). "The results clearly showed that the expression levels of FIBCD1 in BC cell lines (MCF7, MDA-MB-231) were in glucose level-dependent manner: both FIBCD1 gene and protein expression levels under hyperglycemia conditions were higher than that in physiological glucose levels." (PMID 40695783, 2025).
melanoma (1 paper, 2022). A malignant, usually aggressive tumor composed of atypical, neoplastic melanocytes. "Local administration of recombinant Fibcd1 (rFibcd1) ameliorates cachexia-induced myofiber atrophy in the diaphragm of mice bearing patient-derived melanoma xenografts and LLC carcinomas." (PMID 35501350, 2022).
mucositis (1 paper, 2025). Mucositis is inflammation and damage of the mucous membranes lining the mouth and other parts of the gastrointestinal (GI) tract. "This role is further supported by findings from a mouse model, where overexpression of FIBCD1 mitigated chemotherapy-induced weight loss, probably by reducing mucositis and gastrointestinal dysbiosis." (PMID 40813973, 2025).
Parkinson disease (1 paper, 2023). A progressive degenerative disorder of the central nervous system characterized by loss of dopamine producing neurons in the substantia nigra and the presence of Lewy bodies in the substantia nigra and locus coeruleus. "Furthermore, single-cell and spatial transcriptomic sequencing of hippocampal tissue from mice with Parkinson’s disease identified Fibcd1 as one of the highly differentially regulated genes in the CA3 subregion, involved in memory and cognitive functions." (PMID 38090485, 2023).
cancer (11 papers, 2021 to 2025). A tumor composed of atypical neoplastic, often pleomorphic cells that invade other tissues. "They showed that local injection of recombinant secreted Fibcd1 reduces muscle fiber atrophy in the diaphragm muscle caused by cancer cachexia." (PMID 40869331, 2025). "In turn, overexpression of JMJD4 and FIBCD1 has been linked to cancers of the GI tract." (PMID 34151400, 2021). "Fibrinogen C Domain Containing 1 (Fibcd1), a myokine that regulates myofiber size, has been suggested to have a promising role in treatment of cancer cachexia." (PMID 40869331, 2025). "Several genes, including ARRDC5, ELF5, FIBCD1, LINC00494, NLRP7, and L1CAM, have been implicated in various aspects of cancer progression and metastasis." (PMID 39697539, 2024). "Soluble FIBCD1 has been shown to interact with and regulate integrin subunits as well as reduce expression of inflammatory genes in skeletal muscle cells during cancer-induced myofiber atrophy." (PMID 38090485, 2023). "Local injection of recombinant secreted Fibcd1 attenuates myofiber atrophy induced by cancer cachexia in the diaphragm muscle." (PMID 35501350, 2022). "Fibrinogen C domain-containing Protein 1 (Fibcd1), a secreted myokine, impedes the cancer-mediated upregulation of Ddit4." (PMID 36077789, 2022). "Taken together, our study and these recent publications suggest that Fibcd1 reduces tissue inflammation, which is a major driver of cancer-induced muscle wasting." (PMID 35501350, 2022). "A possible explanation for this dichotomy is that FIBCD1 expression by cancer cells impedes local inflammatory responses and hence allows cancer immune escape, which is a key mechanism of cancer progression and metastatic dissemination." (PMID 35501350, 2022). "Further evidence demonstrating that FIBCD1 is a receptor for chondroitin sulfate proteoglycans of the brain extracellular matrix has also been reported, while early data suggest a protective role for soluble FIBCD1 as a myokine in vivo in a model for cancer-induced myofiber atrophy." (PMID 38072065, 2024). "Given the well-established connection between inflammation and cancer development, it is plausible that FIBCD1 may hold anti-carcinogenic properties that stem from its ability to influence early inflammatory responses in the intestinal tract." (PMID 38090485, 2023). "However, paradoxically, high FIBCD1 expression in cancer cells has been found to correlate with poor prognosis and survival in patients with gastric and liver cancer." (PMID 35501350, 2022). "In summary, our study indicates that Fibcd1 may help reinstate myofiber size in the diaphragm muscle, which is a key muscle impacted by cancer cachexia." (PMID 35501350, 2022). "Through comprehensive genomic, epigenomic, and transcriptomic dissections, we pinpointed ARRDC5, ELF5, FIBCD1, LINC00494, NLRP7, and L1CAM as possible prognostic indicators across multiple cancer types." (PMID 39697539, 2024). "In this study, we examined the expression patterns of seven core genes (ARRDC5, ELF5, FIBCD1, LINC00494, NLRP7, L1CAM) across multiple cancer types using a combination of unpaired and paired samples, along with data from the TCGA-GTEx datasets." (PMID 39697539, 2024). "The promising role of a new myokine, fibrinogen C domain containing 1 (FIBCD1), in maintaining muscle mass in patients with cancer was very recently identified." (PMID 38136400, 2023). "The exogenous administration of recombinant FIBCD1 in cachectic mice with Lewis lung carcinoma or melanoma, mitigated the cancer-related muscle atrophy, without promoting tumour growth and progression." (PMID 38136400, 2023). "Fibcd1-induced signaling appears to be muscle selective because rFibcd1 increases ERK activity in myotubes but not in several cancer cell lines tested." (PMID 35501350, 2022). "Interestingly, Fibcd1 increases ERK activity in myotubes but not in several cancer cells, although there are exceptions." (PMID 35501350, 2022).
infection (2 papers, 2023 to 2024). The state of being infected such as from the introduction of a foreign agent such as serum, vaccine, antigenic substance or organism. "Also, it has been speculated that FIBCD1 might modulate a distinct yet not fully understood immune response against A. fumigatus, especially via opsonization and chemo attraction of neutrophils to the site of infection." (PMID 36888604, 2023).
neurodevelopmental disorder (2 papers, 2022 to 2024). A behavioral and cognitive disorder with onset during the developmental period that involves impaired or aberrant development of intellectual, motor, or social functions. "Here, we report deleterious variants in the gene FIBCD1 in two unrelated patients presenting with undiagnosed neurodevelopmental disorders." (PMID 35916241, 2022). "Mutations in the gene FIBCD1 were identified in two unrelated patients with undiagnosed neurodevelopmental disorders." (PMID 35916241, 2022). "While the function of CG6788 is unknown, loss of function mutations in FIBCD1 is associated with neurodevelopmental disorders in humans." (PMID 38098286, 2024).
tumor (2 papers, 2023 to 2025). "On the other hand, high levels of FIBCD1 expression in tissue samples from patients with gastric and hepatic cancer have been associated with increased tumor size and invasiveness as well as overall poorer prognosis and survival." (PMID 38090485, 2023). "The results showed that, compared with control cells, silencing of FIBCD1 decreased BC tumor weight and tumor volume growth under diabetic conditions." (PMID 40695783, 2025). "Among the top-scoring DEGs in BC-DM tumors, FIBCD1 was the most significantly dysregulated gene, and the higher expressions of FIBCD1 gene and protein in BC-DM tumor tissues were further verified by qRT-PCR and IHC assays." (PMID 40695783, 2025). "Nevertheless, the anti-tumor properties of FIBCD1 were evident in the AOM/DSS model, suggesting an alternative mechanism for the protective effect of FIBCD1 in inflammation-associated carcinogenesis." (PMID 38090485, 2023). "Consistent with our IHC data, the expression data show a highly variable but significant increase in FIBCD1 expression in tumor tissues compared to normal controls (p=0.01)." (PMID 38090485, 2023). "Taken together, the present study using an AOM/DSS-induced CAC mouse model found that overexpression of FIBCD1 in the intestinal epithelium resulted in decreased inflammation and tumor formation." (PMID 38090485, 2023). "In human material from CRC patients, we identified expression of FIBCD1 in the tumor tissues where expression and distribution were found to correlate with the disease stage, supporting a possible role for FIBCD1 in human CRC." (PMID 38090485, 2023). "While knockdown of FIBCD1 suppressed BC tumor growth in diabetic mice." (PMID 40695783, 2025). "However, direct assessment of the tissue specimens based on disease progression revealed a significant increase in FIBCD1 expression and distribution at more advanced tumor staging (p < 0.0398)." (PMID 38090485, 2023). "To further assess the effects of FIBCD1 on CAC tumor progression, we analyzed the isolated tumor tissues from AOM/DSS-treated WT and TG littermates for the expression of CAC-related oncogenes and tumor suppressor genes as well as genes involved in cell proliferation and apoptosis." (PMID 38090485, 2023). "Finally, we demonstrate increased expression of FIBCD1 by immunohistochemistry in human CRC specimens at more developed tumor stages." (PMID 38090485, 2023). "On the other hand, overexpression of FIBCD1 did not exhibit a notable impact on the expression of genes associated with tumor development or suppression." (PMID 38090485, 2023). "Importantly, we demonstrated that inhibition of FIBCD1 could suppress BC tumor growth in diabetic mice." (PMID 40695783, 2025). "Collectively, these findings suggest that FIBCD1 influences early inflammatory responses in the AOM/DSS model, leading to a reduction in tumor size and burden." (PMID 38090485, 2023). "As inflammation is instrumental in tumor development in CAC, the ability of FIBCD1 to modulate and dampen inflammatory responses in the intestinal tract may be one of its primary anti-tumorigenic actions observed in the AOM/DSS model." (PMID 38090485, 2023).
FIBCD1 also shares sentences with these, for which no sentence is quoted: breast carcinoma (2 papers); hepatocellular carcinoma (2); Anxiety (1); Diabetes (1); neurodegenerative disease (1); pneumonia (1); sinusitis (1).